NME9 (NME/NM23 family member 9)
Description:
May be a regulator of microtubule physiology.
Synonyms: Txl-2; TXL2; TXNDC6; NM23-H9; NXL2
Tractability: Small molecule: a structure with a bound ligand is known.
Gene: Protein-coding gene on chromosome 3 (138,261,437 to 138,331,354, reverse strand). Ensembl gene ENSG00000181322.
Subcellular location: Cytoplasm, cytoskeleton, cilium axoneme; Dynein axonemal particle
Subcellular location (Human Protein Atlas): Cytosol; Centriolar satellite
Gene Ontology:
Molecular function: nucleoside diphosphate kinase activity
Biological process: CTP biosynthetic process; GTP biosynthetic process; UTP biosynthetic process
Cellular component: dynein axonemal particle; axoneme
Genetic constraint (gnomAD): Loss-of-function variants: 24 observed, 24.23 expected, observed/expected ratio (o/e) 0.99, 90% interval 0.72 to 1.39. The upper end of that interval is the gene's LOEUF score, 1.39, which puts it in group 5 of 6, group 1 being the genes least tolerant of losing a copy. Missense variants: 215 observed, 275.83 expected, observed/expected ratio (o/e) 0.78, 90% interval 0.7 to 0.87. Synonymous variants: 87 observed, 102.66 expected, observed/expected ratio (o/e) 0.85, 90% interval 0.71 to 1.01.
Homologues: Orthologues: chimpanzee NME9 (100% identical), macaque NME9 (97% identical), dog NME9 (83% identical), guinea pig NME9 (82% identical), rabbit NME9 (80% identical), mouse Nme9 (78% identical), pig NME9 (64% identical), tropical clawed frog nme9 (58% identical), zebrafish nme9 (57% identical). Paralogues in human: NME8 (34% identical), NME7 (11% identical), NME4 (8% identical), NME6 (8% identical), NME3 (8% identical), NME5 (8% identical), NME1 (6% identical), NME2 (6% identical).
Diseases named in the same sentence as NME9 in open-access papers:
NME9 is named in the same sentence as 6 diseases in open-access papers, as found by Europe PMC text mining. Sharing a sentence is not in itself a finding about the gene and the disease.
NME9 shares sentences with these, for which no sentence is quoted: cancer (2 papers); colon cancer (1); diffuse large B-cell lymphoma (1); Hypertension (1); lymphoma (1); tumor (1).